PIK3CA (phosphatidylinositol-4,5-bisphosphate 3-kinase catalytic subunit alpha)
Diseases named in the same sentence as PIK3CA in open-access papers (continued):
Sharing a sentence is not in itself a finding about the gene and the disease.
cervical carcinoma (continued). "Consistent with the higher mutation frequency of MMR and proofreading polymerases mutations and the known association of MSI with high total mutation burden (TMB), PIK3CA mutated cervical cancers display a higher TMB than PIK3CA wild-type counterparts." (PMID 33435133, 2021). "PIK3CA was one of the most frequently mutated genes associated with cervical carcinoma and had been observed in our cohort." (PMID 34221990, 2021). "Trials of combinations of PD-1 inhibitors with other targeted therapies such as PI3K inhibitors, guided by molecular markers such as PIK3CA mutations, should be considered as one of the next steps of cervical cancer therapeutics." (PMID 33435133, 2021). "Among frequently mutated genes in squamous cervical cancers, several display higher prevalence of mutations in 3q26-amplified cervical cancers, as defined by amplifications of PIK3CA gene." (PMID 34436017, 2021). "In line with this, cervical cancer cells with PIK3CA mutations and increased AKT activation, such as CaSki cells, exhibited lowest responsiveness toward (chemo)radiotherapy." (PMID 34469022, 2021). "In a cohort of 89 patients with high-risk early-stage cervical cancer who underwent post-operative radiotherapy, a PIK3CA mutation was the most frequently detected aberration (29.2%) but displayed no prognostic impact." (PMID 34830902, 2021). "In contrast to MSI, chromosomal instability as measured by AS is lower in PIK3CA mutated cervical cancers compared to PIK3CA wild-type counterparts." (PMID 33435133, 2021). "PIK3CA mutations resulting in aberrant AKT activation in cervical cancer patients have been associated with worse prognosis after chemoradiotherapy." (PMID 34469022, 2021). "This article examines the landscape of PIK3CA mutated cervical cancers and compares it with that of PIK3CA wild-type carcinomas." (PMID 33435133, 2021). "Next, we found that higher expression of the FSCN1 gene in cervical cancer and head and neck cancer patients with PIK3CA alterations was associated with poorer overall survival and radiotherapy response." (PMID 34249689, 2021). "Common hotspot mutation of PIK3CA, PIK3CA-E545K mutation has also been found to enhance DNA repair in cervical cancer cells as demonstrated by fewer pH2A.X foci and more highly activated Chk1/Chk2, regulators of DDR in mutated cells." (PMID 34737943, 2021). "Through the analysis of TCGA data of patients with cervical cancer (291 cases) and head and neck cancer (488 cases), we found that PIK3CA was a highly altered gene (including activating mutations and amplification)." (PMID 34249689, 2021). "We analyzed TCGA clinical data and found high-frequency mutations or amplifications of the PIK3CA gene in patients with cervical cancer and head and neck cancer." (PMID 34249689, 2021). "Somatic mutations in the PIK3CA denoted a late event during cervical carcinogenesis, and have been detected in multiple cervical carcinoma subgroups." (PMID 34277697, 2021). "Tumor shrinkage (− 11.9%, − 6.1%) was observed in two patients (one with cervical cancer; one with peritoneal cancer) who had PIK3CA mutation in the helical domain (E542K or E545K) and/or amplification." (PMID 31227862, 2019). "Among the HPV-negative cervical cancer patients, two (28.57 %) were positive for PIK3CA mutation and only one (4.76 %) tested positive among the HPV-positive cervical cancer patients." (PMID 31350972, 2019). "The distribution of the various HPV integration signatures differed between ASCC and cervical cancers and was associated with viral load and PIK3CA mutation." (PMID 31766658, 2019). "In cervical cancer patients, mutations in PIK3CA gene was found to be associated with worse overall survival and cancer-specific survival." (PMID 31350972, 2019).
cervical carcinoma (continued). "Recent studies have reported that SC66 has shown a strong anti-tumor activity, including hepatocellular carcinoma and cervical cancer with PIK3CA R88Q and PTEN R233* mutation." (PMID 31168297, 2019). "This is consistent with the study conducted among Chinese population where 13.6% (105 of 771) of patients with resected cervical cancer harbored non-synonymous PIK3CA mutations." (PMID 31350972, 2019). "PIK3CA mutations were observed in 10% of bladder cancer patients and are associated with cisplatin resistance and a migratory phenotype in cervical cancer cells." (PMID 31905960, 2019). "Among HPV-negative cervical cancer patients, two (28.57%) were positive for PIK3CA mutation while among HPV-positive cervical cancer patients, only one (4.76 %) tested positive for PIK3CA mutation." (PMID 31350972, 2019). "Our data illustrated that, compared to primary tissue, derived HeLa, ME180 and CaSki cell lines, originally established from metastatic sites of cervical cancer, harbored the PIK3CA E545K mutation." (PMID 31295843, 2019). "Overall, the distribution of mechanistic signatures of HPV insertions in ASCC was different from that observed in cervical carcinoma and was associated with viral load and PIK3CA mutation." (PMID 31766658, 2019). "The induction of mutations and/or the amplification of PIK3CA are frequent events found in advanced cervical cancers." (PMID 31295843, 2019). "PIK3CA gene was found mutated in three (10.71 %) out of 28 cervical cancer patients included in this study." (PMID 31350972, 2019). "The exon 9 of PIK3CA gene was found mutated in three (10.71%) out of 28 cervical cancer patients included in this study." (PMID 31350972, 2019). "One previous study about genetic alterations in cervical cancer patients determined that PIK3CA has the highest gene mutation rates among all other cancer-associated genes included in their study." (PMID 31350972, 2019). "We analyzed PIK3CA mutation in 59 patients with stage IIB to IVA cervical carcinomas primarily treated by CCRT with weekly cisplatin using formalin-fixed paraffin-embedded biopsy specimens before treatment." (PMID 30075505, 2018). "Taken together, PIK3CA E542K and E545K mutations play a positive role in promoting the nuclear accumulation of β-catenin in cervical cancer cells." (PMID 30547809, 2018). "In a previous study, we demonstrated that E545K, E542K (helical domain), and H1047R (kinase domain) were the hotspots of PIK3CA mutation in cervical cancer." (PMID 30547809, 2018). "In cervical cancer, PIK3CA has been identified as one of the most commonly mutated genes, and the mutation rate ranges from 10 to 30%." (PMID 30547809, 2018). "Considering the similar effect of PIK3CA E542K and E545K mutations on glucose metabolism and proliferation, we confirmed the effects of PIK3CA E545K mutation in cervical cancer xenografts." (PMID 30547809, 2018). "In the present study, we demonstrate that PIK3CA mutations promoted glucose metabolism and cervical cancer cell proliferation in vivo and in vitro." (PMID 30547809, 2018). "The proliferative and glycolytic potential was enhanced in cervical cancer with PIK3CA E542K and E545K mutations in vivo and in vitro." (PMID 30547809, 2018). "The aim of this study was to clarify the prognostic significance of PIK3CA mutational status in cervical cancers treated by CCRT." (PMID 30075505, 2018). "Taken together, PIK3CA E542K and E545K mutations enhance glucose metabolism and proliferation in cervical cancer cells." (PMID 30547809, 2018). "PIK3CA mutations were detected in 146 of the total 990 patients with cervical cancer (146/990, 14.7%), including 132 mutations at exon 9 (132/990, 13.3%) and 14 mutations at exon 20 (20/990, 1.4%)." (PMID 30547809, 2018). "The study aims to present the effect of PIK3CA E542K and E545K mutations on glucose metabolism and proliferation and identify their underlying mechanisms in cervical cancer." (PMID 30547809, 2018).
cervical carcinoma (continued). "Together with previous published findings, the current study further supports the clinical significance of PIK3CA mutation in cervical cancer." (PMID 30075505, 2018). "The two patients with cervical cancer treated with everolimus who achieved disease stabilization that lasted longer than 6 months had either a PIK3CA mutation (Glu542Lys) or a PTEN heterozygous deletion with a loss of protein expression." (PMID 32914004, 2018). "Among these patients, only 2 obtained a PR (one endometrioid cancer of the ovary and one cervical cancer with either PIK3CA or AKT1 mutation) and one got a SD (endometrioid cancer of the ovary with PIK3CA mutations)." (PMID 28008141, 2017). "PTEN mutations are less frequent than PIK3CA mutations but are found in 6–13% of cervical carcinomas and 6–10% of HPV-positive head and neck cancers." (PMID 28771191, 2017). "For example, PIK3CA-mutated cervical cancers have worse prognosis than cancer with wild-type PIK3CA." (PMID 28771191, 2017). "Gain of function mutations in the PIK3CA gene (encoding p110α) has been found to be oncogenic and is implicated in cervical cancers." (PMID 27716847, 2016). "In concordance with this, low fractions of cells harbouring PIK3CA mutations were found in invasive cervical carcinomas, indicating PIK3CA mutations are only present in subclones of the tumour." (PMID 29074190, 2016). "Our results suggest that the PIK3CA-E545K mutation is associated with an enhanced migratory phenotype in cervical cancer cells." (PMID 27489350, 2016). "Recent profiling of 301 cervical carcinomas using a mass spectrometry-based panel of known somatic mutations (GynCarta 2.0, Sequenom) revealed frequent mutations in PIK3CA (SCC 25%, AdCA 3%) and KRAS (SCC 11%, AdCA 24%)." (PMID 29074190, 2016). "A study from Latin America reported mutations in PIK3CA to be a key player both in squamous and adeno cervical carcinomas." (PMID 27829003, 2016). "Another study on cervical cancer cases of European origin identified PIK3CA, KRAS and FBXW7 to be the most mutated." (PMID 27829003, 2016). "To better understand the effects of PIK3CA-E545K mutation on cervical cancer cells, we first examined the effects of IR and cisplatin on survival of a panel of cervical cancer cell lines." (PMID 27489350, 2016). "We showed that one or more somatic mutations occurred in 36% of cervical carcinomas, most of them in PIK3CA (24%), followed by KRAS (4%), CTNNB1 (3%), and PPP2R1A (3%)." (PMID 26197069, 2015). "The aim of this study was to evaluate the clinicopathological and prognostic relevance of PIK3CA mutations in Chinese patients with surgically resected cervical cancer." (PMID 26358014, 2015). "The prevalence of PIK3CA mutations in our cohort of 771 patients with FIGO stage IB/IIA cervical cancer was determined by RT-PCR–based direct sequencing." (PMID 26358014, 2015). "Our study is the first large cohort study to investigate the clinicopathological and prognostic relevance of PIK3CA mutations in patients with surgically resected cervical cancer." (PMID 26358014, 2015). "PIK3CA mutations were screened in 771 cervical cancer specimens using reverse transcription polymerase chain reaction and Sanger sequencing." (PMID 26358014, 2015). "Our multivariate analyses revealed that PIK3CA mutation in cervical cancer was an independent predictor for better RFS (HR = 0.54, 95% CI: 0.29–0.99, P = 0.048)." (PMID 26358014, 2015). "It is necessary to conduct PIK3CA mutational analyses in a large cohort of cervical cancer patients." (PMID 26358014, 2015). "The highest and lowest estimates of PIK3CA mutation frequencies in cervical cancers (5.7 and 37.5%) have been obtained using Sequenom massARRAY technology, which has a sensitivity threshold of ~5%." (PMID 26209091, 2015). "Most studies of KRAS and PIK3CA mutations in cervical cancer have combined PCR amplification across mutation hotspot regions with Sanger sequencing." (PMID 26209091, 2015).
cervical carcinoma (continued). "In gynecologic malignancies, phosphoinositide-3-kinase, catalytic, alpha polypeptide (PIK3CA) mutations are found in 23%, 10% and 12% of endometrial, ovarian, and cervical cancers, respectively." (PMID 24742900, 2014). "We analyzed the outcomes of patients with metastatic or recurrent cervical carcinomas who had a test for PIK3CA mutation and/or PTEN loss/mutation, and received ≥1 phase I therapeutic regimen between January 2006 and June 2013." (PMID 25426553, 2014). "We then selected the cervical cancer cell line C33A, which is mutated for both PIK3CA and PTEN (PIK3CA R88Q, PTEN R233*) and expresses high levels of p-AKT at baseline, to assess the response to two allosteric AKT inhibitors, SC-66 and MK-2206." (PMID 24705275, 2014). "In cervical cancer however, mutations almost exclusively occur on loci on exon 9 (47 out of 50 (94%) PIK3CA mutations)." (PMID 24671188, 2014). "In cervical cancer patients, PIK3CA emerged as the most frequently mutated gene." (PMID 41602395, 2026). "PIK3CA is one of the most frequently mutated genes in cervical cancer (CC)." (PMID 41958669, 2026). "PIK3CA is another frequently mutated gene in HPV-independent cervical cancer." (PMID 41155343, 2025). "Another recent case suggests that the PI3KCA-E545K mutation enhances PD-L1 expression by upregulating PD-L1 transcription factor interferon regulatory factor 1 and that the PIK3CA mutation may be a biomarker for pembrolizumab treatment in cervical cancer." (PMID 38215117, 2024). "Among the various oncogenes implicated in cancer, PIK3CA expression is known to cause cervical cancer, suggesting that inhibiting PIK3CA may impede cervical cancer progression." (PMID 39590348, 2024). "PI3KCA-E545K mutation enhances PD-L1 expression by upregulating PD-L1 transcription factor interferon regulatory factor 1 and that the PIK3CA mutation could be a biomarker for PD-1 blockade treatment in cervical cancer." (PMID 38215117, 2024). "Thus, mutation or alteration in the expression of MYC and PIK3CA is frequently associated with development of cervical cancer." (PMID 36763589, 2023). "Besides, mutations of PIK3CA E542K and PIK3CA E545K are known to endorse proliferation and glycolysis of cervical cancer." (PMID 37596643, 2023). "Moreover, previous studies on the genomic landscape of cervical cancer have identified frequent alterations in genes, such as PIK3CA, EP300, FBXW7, and APOBEC signatures, associated with the process of carcinogenesis of virus-associated diseases." (PMID 37256181, 2023). "A study on combination therapy targeting activated ERBB2 and PIK3CA mutations in cervical cancer found that the majority of cervical tumors could benefit from existing ERBB2/PIK3CA/AKT/mTOR-targeted drugs." (PMID 35778737, 2022). "PIK3CA mutation status was significantly related to median tumor size and significantly correlated to decreased disease-free survival and overall survival in cervical cancer." (PMID 35646104, 2022). "Notably, three recurrent mutations in the PIK3CA gene were located in the essential protein-coding region, such as E545K and E542K, which are reported to confer radioresistance to cervical cancer." (PMID 35205332, 2022). "PIK3CA mutations occurred most frequently in the overall patient group, and the mutation rate in our study was higher than the rates in previous studies of cervical carcinoma from the Netherlands (20%), France (27%), Latin America (28–33%), the USA (31%) and Norway (15%)." (PMID 36333792, 2022). "Noticeably, the PIK3CA mutation is related to the resistance of cervical cancer to the treatment." (PMID 33557879, 2021). "In cervical cancer, PIK3CA was a prognostic biomarker and associated with poor overall survival." (PMID 34367282, 2021). "There is, for example, a suggestion from preclinical studies that PIK3CA mutations may sensitize cervical cancer cells to PARP inhibitors." (PMID 33435133, 2021).
cervical carcinoma (continued). "PI3K inhibitors are already in the clinic for other cancers and, given the high prevalence of PIK3CA mutations in the disease, as ascertained in the current study, they could be prioritized for further development in cervical carcinomas." (PMID 33435133, 2021). "In this study, five different genomic regions within the top three most frequently mutated genes (EGFR, KRAS and PIK3CA) in COSMIC database with a key role in the development of cervical cancers were selected to study the mutation frequency in Bangladeshi patients." (PMID 33736612, 2021). "Since HPV(+) head and neck cancers have driving mutations and cancer pathways in common with cervical cancers, including PIK3CA, FAT1, CASP8, PTEN, etc., comparing the subtypes of HPV(+) HNSCC with those of cervical cancer may reveal additional insights." (PMID 34072836, 2021). "In this study, PIK3CA mutation (10.71%) was only found among cervical cancer patients." (PMID 31350972, 2019). "Amplification of PIK3CA has been associated with pathogenesis of cervical cancer." (PMID 31905960, 2019). "Additionally, MGL ligand expression correlated to the occurrence of PIK3CA mutations, the most frequently observed oncogenic alteration in cervical cancer." (PMID 30761272, 2019). "Activating mutations or a copy number gain of PIK3CA at 3q26 encoding PI3K-p110α are the most significantly consistent chromosomal alterations found in primary cervical cancer, highlighting its important role in the progression of dysplastic uterine cervical cells to invasive cancer." (PMID 31295843, 2019). "Additionally, MGL ligand expression is correlated to PIK3CA mutations, the most frequent oncogenic mutation in cervical cancer." (PMID 30761272, 2019). "Furthermore, the association between MGL ligand expression and oncogenic PIK3CA mutations suggest a causative role of PIK3CA mutation in MGL ligand expression in cervical cancer." (PMID 30761272, 2019). "Based on a The Cancer Genome Atlas (TCGA) database, significant PIK3CA alterations were analyzed, such as mutations, amplification and deletions, which revealed a relatively high frequency of alterations across multiple cancers, including cervical cancer." (PMID 31295843, 2019). "All cervical cancer patients were analyzed for PIK3CA mutation." (PMID 31350972, 2019). "However, PIK3CA mutation positivity rate was relatively low among HPV-positive cervical cancer patients." (PMID 31350972, 2019). "Thus, PIK3CA E545K mutation has a positive impact on glucose metabolism in cervical cancer xenografts." (PMID 30547809, 2018). "A luciferase assay was used to determine whether SIRT3 promotor was regulated by β-catenin in cervical cancer cells with PIK3CA E542K and E545K mutations." (PMID 30547809, 2018). "Considering the high activation of AKT/GSK3β/β-catenin in cervical cancer cells with mutant PIK3CA, we inferred that PIK3CA E542K and E545K mutations might promote the nuclear accumulation of β-catenin in cervical cancer cells." (PMID 30547809, 2018). "However, to date, only a few studies have reported the prognostic significance of PIK3CA mutation in cervical cancers treated by CCRT." (PMID 30075505, 2018). "Thus, it was necessary to explore the effect of PIK3CA mutation on proliferation and metabolism alterations in cervical cancer." (PMID 30547809, 2018). "Together with the previously published findings, the current observations further suggest that molecular inhibitors targeting the PI3K/Akt pathway may improve the outcome by cisplatin-based CCRT in locally advanced cervical cancers harboring PIK3CA mutation." (PMID 30075505, 2018). "A previous study demonstrated that PIK3CA was the most common mutated gene in cervical cancer." (PMID 30547809, 2018). "Hence, the aim of the current study was to clarify the prognostic significance of PIK3CA mutational status in cervical cancers treated by CCRT with weekly cisplatin." (PMID 30075505, 2018).